CLU (clusterin)
Diseases named in the same sentence as CLU in open-access papers (continued):
Sharing a sentence is not in itself a finding about the gene and the disease.
Alzheimer disease (continued). "Given these associations with Alzheimer’s disease and MS, and the known role of clusterin in multiple CNS pathologies, interrogating effects of clusterin on OPC function is useful for our understanding of how these cells may be affecting disease progression." (PMID 35902669, 2022). "Moreover, the presence of the single nucleotide polymorphism (SNP) rs11136000 in the CLU gene is associated with reduced risk of late-onset Alzheimer's disease (LOAD), which is more frequent in female than in male subjects." (PMID 36071866, 2022). "Although previous genome-wide association studies (GWAS) have reported a potential protective effect of CLU on Alzheimer’s disease (AD) patients, how intron-located rs11136000 (CLU) affects AD risk by regulating CLU expression remains unknown." (PMID 36033622, 2022). "PICALM and CLU genes have been linked to alterations in brain biochemical processes that may have an impact on Alzheimer’s disease (AD) development and neurophysiological dynamics." (PMID 34650147, 2021). "Several recent studies demonstrated that CSF and circulatory clusterin levels serve as a prognostic and/or diagnostic biomarker for neuropathologies such as Alzheimer’s disease (AD), mild cognitive impairment, multiple sclerosis, acute ischemic stroke, and epilepsy." (PMID 31882899, 2019). "CLU polymorphisms were recently found to be associated with Alzheimer’s disease." (PMID 30967152, 2019). "Adding to this hypothesis is a study showing that clusterin is up-regulated in the cerebrospinal fluid (CSF) of Alzheimer's disease individuals and that higher CSF clusterin was associated with an increase in entorhinal cortex atrophy." (PMID 31853523, 2019). "In this study, we tested the hypothesis that clusterin and ApoE4 work together to cause synapse degeneration in Alzheimer's disease by increasing accumulation of oligomeric amyloid beta at synapses." (PMID 31853523, 2019). "We tested the hypothesis that genetic variation in CLU is associated with risk of Alzheimer’s disease, all dementia, vascular dementia, ischemic cerebrovascular disease, and ischemic heart disease in the general population." (PMID 29534716, 2018). "The data represent the frequencies of alleles, genotypes and haplotypes for single nucleotide polymorphisms (SNPs) rs2279590 and rs1532278 in human clusterin gene (CLU) associated to Alzheimer's diseases in previously published genome-wide and candidate genes association studies." (PMID 29276745, 2018). "Like the ε4 allele of the apolipoprotein E gene (APOE), the clusterin gene (CLU) is a risk locus for Alzheimer’s disease, and may play additional roles in atherosclerosis pathogenesis." (PMID 29534716, 2018). "Interestingly, increased blood levels of Clusterin are associated with atrophy of the entorhinal cortex in Alzheimer’s disease for which this protein seems to be a marker of disease severity." (PMID 27362861, 2016). "Brain clusterin is known to be associated with the amyloid‐β deposits in Alzheimer's disease (AD)." (PMID 25940137, 2016). "The next highest DES-ranked gene, CLU (clusterin), is associated with clearance of cellular debris, lipid recycling, apoptosis, and, as a stress-induced secreted chaperone protein, has been genetically associated with late-onset Alzheimer’s disease." (PMID 26636579, 2015). "The CLU gene has been identified as an important novel risk locus for Alzheimer’s disease." (PMID 26179372, 2015). "The CLU gene is one of the prime genetic candidates associated with Alzheimers disease." (PMID 24244428, 2013). "Clusterin, a glycoprotein implicated in Alzheimer’s disease (AD), remains unclear." (PMID 37941999, 2023). "Although the biological role of clusterin remains to be fully understood, it is undeniable that increased clusterin concentrations are associated with homeostasis disorders in many pathophysiological conditions, including atherosclerosis, obesity, diabetes, and Alzheimer's disease (AD)." (PMID 36071866, 2022).
Alzheimer disease (continued). "We investigated the effect of an AD risk variant (rs7982) in the 5th exon of CLU on alternative splicing by using an integrative approach of brain-tissue-based RNA-Seq and whole genome sequencing data from Accelerating Medicines Partnership—Alzheimer’s Disease (AMP-AD)." (PMID 32992916, 2020). "Recently, we showed that in Alzheimer's disease (AD) model mice and human postmortem brains, there are elevated levels of methionine-oxidized clusterin in the disease state versus controls." (PMID 41750649, 2026). "The siRNA-NP targeting diverse molecular mechanisms implicated in Alzheimer's disease, to downregulate genes such as bridging integrator 1 (BIN1), sortilin-related receptor 1 (SORL1), and clusterin (CLU) has proven useful in various animal models." (PMID 41356731, 2025). "To investigate the impact of Clusterin on OPCs in the context of Alzheimer’s disease, we employed a combination of immunofluorescence and transmission electron microscopy techniques, primary culture of OPCs, and an animal model of Alzheimer’s disease." (PMID 38853911, 2024). "Within the brain, clusterin is the second most abundantly expressed apolipoprotein putatively involved in Alzheimer’s disease, and it is significantly correlated with progression." (PMID 39064171, 2024). "MI also elevated aggregate constituents enriched in Alzheimer’s disease (AD) aggregates, such as proteasomal subunits, heat-shock proteins, complement C3, clusterin/ApoJ, and other apolipoproteins." (PMID 37922111, 2024). "Proteins known to be involved in Alzheimer’s disease progression, (such as CLU, APOE, and ADAM10) and Parkinson’s Disease (such as PARK7 and VPS35) were also identified, suggesting a potential role of GDE2-released EVs in neurodegeneration." (PMID 39272985, 2024). "In a study in which the cerebrospinal fluid of patients with Alzheimer’s disease (n = 99) and control subjects (n = 39) was analyzed, patients with AD presented higher clusterin content." (PMID 38542375, 2024). "A study on late-onset Alzheimer’s disease focusing on protein–protein network interactions revealed eight genes with strong associations: APOE, SORL1, APOC1, CD33, CLU, TOMM40, CNTNAP2, and CACNA1C." (PMID 39228919, 2024). "Clusterin (CLU), or APOJ, is a multifunctional secretory glycoprotein implicated in several physiological and pathological states, including Alzheimer’s disease (AD)." (PMID 38542375, 2024). "This association was modified by allelic variants in genes ABCA7, CLU, BDNF and MS4A6A that have been previously linked to Alzheimer’s disease." (PMID 37658429, 2023). "We uncovered a significant enrichment for processes regulating amyloid-beta formation, revealing that hc-RAE expression impacts Alzheimer’s disease risk genes that include APOE, ABCA7, CLU, NTRK2, and more." (PMID 36640362, 2023). "Several studies have used MRM to obtain detailed expression profiles of sEV proteins and to identify potential biomarkers such as HSP90 and syndecan-1 in bladder cancer, and annexin A2 and clusterin in Alzheimer's disease." (PMID 36797736, 2023). "Mechanically, the complement cascade inhibitor CLU in plasma reduces neuroinflammatory gene expression in a mouse model of acute brain inflammation and a mouse model of Alzheimer's disease." (PMID 35788904, 2023). "Apolipoprotein E (APOE) and clusterin (CLU) involved in cholesterol transport and metabolism, are associated with an increased risk of Alzheimer’s disease (AD), indicating the underlying predictive roles of cholesterol metabolism in cognitive decline." (PMID 35982405, 2022). "Intravenously injected clusterin binds to brain endothelial cells and can reduce neuroinflammatory gene expression in a mouse model of acute brain inflammation and Alzheimer’s disease." (PMID 36389059, 2022). "Reelin depletion is regarded as an early phenomenon in Alzheimer’s disease, whereas clusterin promotes amyloid beta clearance." (PMID 35457118, 2022).
Alzheimer disease (continued). "Clusterin and ApoE limit amyloid retention in Alzheimer’s disease and mitigate cerebral microbleeds." (PMID 36289630, 2022). "Genome wide association studies (GWAS) have identified Alzheimer’s disease risk single nucleotide polymorphisms (SNPs) in complement receptor 1 (CR1), clusterin (CLU) and C1S." (PMID 35794654, 2022). "Recent studies have revealed the ability of VLDLR to interact with multiple ligands and molecules such as reelin and clusterin, which are correlated with Alzheimer’s disease." (PMID 35457118, 2022). "Plasma protein profiling of mild cognitive impairment and Alzheimer’s disease using iTRAQ quantitative proteomics identified apolipoproteins including clusterin (APOJ), transferrin, and Inter-alpha-trypsin inhibitor (ITIH4)." (PMID 34182925, 2021). "We report on the fabrication and characterisation of graphene field-effect transistor (GFET) biosensors for the detection of Clusterin, a prominent protein biomarker of Alzheimer’s disease (AD)." (PMID 33869287, 2021). "Baseline participant characteristics as stratified by Apolipoprotein E (APOE) genotype (ε4-/ε4+) and Alzheimer’s disease genetic risk score (AD-GRS; Clusterin + Complement receptor 1+ Phosphatidylinositol-binding clathrin assembly protein)." (PMID 34603005, 2021). "Clusterin can bind Aβ, prevent fibrillization of Aβ, and prevent the loss of long-term potentiation and memory when injected into a rat, which points towards a protective role for clusterin in Alzheimer's disease." (PMID 31853523, 2019). "Clusterin (CLU) is a glycoprotein involved in inflammation, proliferation, cell death, neoplastic disease, Alzheimer disease and aging." (PMID 30967152, 2019). "CLU is a stress-activated, ATP-independent molecular chaperone, normally secreted from cells; it is up-regulated in Alzheimer disease as well as in many tumor types." (PMID 31215484, 2019). "We therefore looked at the co-localization of clusterin and Aβ together at the synapse to see if Alzheimer's disease APOE4 cases were more likely to have synapses positive for both markers." (PMID 31853523, 2019). "The data presented here from human post-mortem brain tissue highlight the importance of studying synaptic effects of clusterin and its interactions with pathological proteins in Alzheimer’s disease." (PMID 31853523, 2019). "Clusterin (CLU), or apolipoprotein J (ApoJ), is the third most predominant genetic risk factor associated with late-onset Alzheimer’s disease (LOAD)." (PMID 31738162, 2019). "Jackson and colleagues observe that clusterin accumulates in synapses in human Alzheimer’s disease brain tissue, and that this accumulation is increased in people carrying the Alzheimer’s disease risk gene apolipoprotein E4." (PMID 31853523, 2019). "This is consistent with previous studies, although a recent study indicated that clusterin is increased in Alzheimer's disease due in part to its interaction with Aβ plaques." (PMID 31853523, 2019). "The clusterin molecule is a versatile chaperone that has the ability to bind to a wide array of physiological ligands putatively involved in Alzheimer’s disease pathology." (PMID 29534716, 2018). "Clusterin (CLU) is considered one of the most important roles for pathogenesis of Alzheimer’s Disease (AD)." (PMID 30038359, 2018). "The result was consistent with previous studies showing multiple bands in a study when clusterin was first cloned, in human blood and cerebrospinal fluid (CSF) of patients with Alzheimer’s disease, and in colon cancer cells in vitro." (PMID 28767729, 2017). "Previous reports suggest that clusterin has a permeability effect on the blood-brain-barrier in patients with Alzheimer’s disease (AD)." (PMID 28767729, 2017). "Our study adds to the literature on plasma clusterin and showing for first time, a lower value of clusterin in Alzheimer’s disease." (PMID 27861589, 2016). "More studies are required to ascertain the utility of plasma clusterin as a biomarker in Alzheimer’s disease." (PMID 27861589, 2016).
Alzheimer disease (continued). "Our pilot study shows that plasma clusterin is lower in Alzheimer’s disease with respect to control population." (PMID 27861589, 2016). "Using ROC (Receiver operating characteristic) curve analysis, a plasma clusterin value of 80.8μg/mL had a sensitivity of 76.5% and specificity of 63.2% in differentiating Alzheimer’s disease from control population." (PMID 27861589, 2016). "In the nervous system, the expression of CLU (clusterin) is elevated in neuropathological conditions, such as Alzheimer’s disease, where CLU co-precipitates with APP, suggesting a physiological interaction." (PMID 27748412, 2016). "Studies have shown that clusterin, similar to its predecessor apolipoprotein E (ApoE), plays a vital role in the pathogenesis of Alzheimer's disease (AD)." (PMID 27516739, 2016). "Clusterin is a glycoprotein with known involvement in Alzheimer’s disease that plays a role in preventing inflammation and reducing apoptosis." (PMID 27600232, 2015). "Clusterin participates in Aβ, PrP(res), and α-synuclein aggregation in Alzheimer’s disease, prionpathies, and α-synucleinopathies, respectively." (PMID 24798087, 2015). "Recently, upregulated expression of CLU has been reported in tumor pathogenesis and progression, Alzheimer’s disease, atherosclerosis, renal diseases." (PMID 24885808, 2014). "Clusterin/apolipoprotein J is an abundant plasma chaperone protein that has recently been suggested as a potential biomarker that reflects the inflammatory process in Alzheimer's disease." (PMID 25076422, 2014). "Recently, it has been shown that plasma clusterin correlates with the severity and progression of Alzheimer's disease." (PMID 25076422, 2014). "Amongst the associations identified by this less stringent approach were those for brain levels of CLU, CR1 and GAB2 which were identified as risk loci in GWAS of Alzheimer's disease." (PMID 22685416, 2012). "Clusterin (CLU, APOJ) has been implicated in diseases ranging from cancer to Alzheimer's disease (AD)." (PMID 22506010, 2012). "Recent genome-wide association studies of Alzheimer's disease (AD) have identified variants in BIN1, CLU, CR1 and PICALM that show replicable association with risk for disease." (PMID 21347408, 2011). "More recently, genome-wide association studies showed involvement of the complement lysis inhibitor (Clusterin) gene and of the complement component receptor 1 (CR1) gene in the genetic risk to late onset Alzheimer's disease." (PMID 20862287, 2010). "In neurodegenerative diseases such as Alzheimer’s disease (AD), aberrant splicing of susceptibility alleles in genes like PICALM, CLU, and PTK2B has been implicated in disease progression, further demonstrating the critical role of splicing regulation in age-related disorders." (PMID 40417629, 2025). "Additionally, protein tyrosine kinase 2 beta (PTK2B), clusterin, and cholinergic receptor nicotinic alpha 2 (CHRNA2) genes are considered genetic risk factors for late-onset Alzheimer’s disease." (PMID 41007636, 2025). "Protein tyrosine kinase 2β (PTK2B)/clusterin (CLU) and membrane-spanning 4A (MS4A) were significantly associated with the onset of all-cause dementia, whereas aph-1 homolog B (APH1B) was specifically linked to Alzheimer's disease." (PMID 40949174, 2025). "Previous studies also point towards a protective effect of clusterin against Alzheimer’s disease." (PMID 39001884, 2024). "It remains to be determined exactly which cell types might be contributing to the increase in clusterin observed in Alzheimer’s disease." (PMID 38853911, 2024). "Study of miRNA involvement in Alzheimer’s disease pathogenesis is relevant, since the associations of protein-coding genes (APOE4, ABCA7, BIN1, CLU, CR1, PICALM, TREM2) with the disease revealed as a result of GWAS make it difficult to explain its complex pathogenesis." (PMID 38680184, 2024). "In conclusion, the role of CLU in Alzheimer's disease is complex and not fully understood." (PMID 37122381, 2023).
Alzheimer disease (continued). "Thus, the complex effects of clusterin shown by the Hartl lab in Parkinson’s disease expand to Alzheimer’s disease." (PMID 37731161, 2023). "Clusterin has been proven to play an important role in the pathogenesis of Alzheimer's disease." (PMID 36071866, 2022). "Similar to APLP1, CLU has been described in the pathophysiogenesis of Alzheimer's disease." (PMID 35155457, 2021). "Using NEBULA in Alzheimer’s disease cohort data sets, we found that the cell-level expression of APOE correlated with that of other genetic risk factors (including CLU, CST3, TREM2, C1q, and ITM2B) in a cell-type-specific pattern and an isoform-dependent manner in microglia." (PMID 34040149, 2021). "Neuroinflammation has emerged as a targetable mechanism in Alzheimer’s disease (AD) over the last ten years, which has been driven by GWAS (Genome Wide Association Studies) signals in several genes (CR1, CLU, TREM2, HLA-DRB5/DRB1, INPP5D, and MEF2C) that are implicated in inflammation." (PMID 33352944, 2020). "Another Alzheimer’s disease-associated variant rs9331896-C (MAF = 0.41, PGWAS = 3x10-25) located on chromosome 8p21 within intron 2 of the CLU gene is associated with the individual scores of a component consisting of 38 genes with non-zero scores (P = 1.32x10-4; FDR < 0.15)." (PMID 32012164, 2020). "Clusterin levels are elevated in several neurodegenerative diseases such as amyotrophic lateral sclerosis, multiple sclerosis, transmissible spongiform encephalopathies, Alzheimer`s disease, and Huntington`s disease." (PMID 32084011, 2020). "The molecular chaperone Clusterin (CLU) impacts the amyloid pathway in Alzheimer’s disease (AD) but its role in tau pathology is unknown." (PMID 33261653, 2020). "As Aβ plaques are more prevalent in individuals with an APOE4 genotype one might expect a slight increase in the amount of clusterin in Alzheimer's disease APOE4 cases compared with Alzheimer's disease APOE3 cases." (PMID 31853523, 2019). "It is possible that our observed increased localization of clusterin in synapses in Alzheimer’s disease may have implications beyond local synaptic protein changes." (PMID 31853523, 2019). "Here, we observe clusterin in synapses in human Alzheimer's disease brain." (PMID 31853523, 2019). "A stress response could help explain the increase in the amount of clusterin in Alzheimer’s disease." (PMID 31853523, 2019). "These new individual data provide independent replication of previous GWAS findings that the T allele of rs9331896 is the risk allele for Alzheimer’s disease, and we firmly conclude that CLU is not important for atherosclerosis- related diseases." (PMID 29534716, 2018). "CLU has been shown to be clearly upregulated in astrocytes of the Alzheimer's disease patients." (PMID 30235220, 2018). "The reason for choosing clusterin, and not any of the other Alzheimer’s disease GWAS index variants is that clusterin is a biologically plausible lipid molecule with dual functions in the brain and in the peripheral circulation just like apolipoprotein E." (PMID 29534716, 2018). "Clusterin and beta-amyloid (Aβ) are involved in the pathogenesis of Alzheimer’s disease (AD)." (PMID 29169407, 2017). "It is associated with Lewy bodies in Parkinson’s disease, with the pathology in Alzheimer’s disease and multiple system atrophy, Cerebrospinal fluid levels of clusterin may reflect pathology in neurodegenerative disease." (PMID 28904337, 2017). "We hypothesize that lower clusterin values in Alzheimer’s disease may be interfering with the clearance of amyloid and inhibition of amyloid formation." (PMID 27861589, 2016). "Although abundant genetic and biochemical evidence strongly links Clusterin (CLU) to Alzheimer disease (AD) pathogenesis, the receptor for CLU within the adult brain is currently unknown." (PMID 27378688, 2016). "A larger study on plasma clusterin in Alzheimer’s disease is currently ongoing in our institute." (PMID 27861589, 2016).